S100A2 (S100 calcium binding protein A2)
Diseases named in the same sentence as S100A2 in open-access papers (continued):
Sharing a sentence is not in itself a finding about the gene and the disease.
breast carcinoma (22 papers, 2000 to 2026). "High S100A2 expression was associated with a better prognosis in patients with breast cancer, bladder cancer, melanoma, laryngeal squamous cell carcinoma, and gastric cancer." (PMID 35885660, 2022). "In contrast, lower S100A2 expression is associated with an unfavorable clinical course in patients with renal cell carcinoma, breast cancer, bladder cancer, melanoma, and gastric cancer." (PMID 35885660, 2022). "S100A2 is expressed in 37% of specimens of carcinoma in situ, and in <15% of breast cancer samples in vivo, suggesting that the loss of S100A2 is related to the development of breast cancer and does not appear to be with an early phase of tumor development." (PMID 35885660, 2022). "Others showed that the S100A2 was expressed in normal breast tissue but it was down-regulated during breast cancer progression." (PMID 39594999, 2024). "For example, through a comprehensive analysis of information from multiple patients, S100A2 was identified as a potential predictor of breast cancer." (PMID 34148033, 2021). "Previous studies have shown that S100A2 plays an anticancer role in oral cancer, prostate cancer, breast cancer, and lung cancer, while it acts as a cancer promoter in ovarian cancer, gastric cancer, and esophageal squamous carcinoma." (PMID 34804125, 2021). "Meanwhile,a down-regulation of S100A2 can be verified in many human cancers and certified as a prognostic marker, such as melanoma, prostate and breast cancer." (PMID 30558666, 2018). "The role of S100A2 as a tumor suppressor is supported by study of BRCA1 mutant and basal-like breast cancer cell lines, in which S100A2 exogenous expression resulted in growth inhibition, while siRNA knockdown enhanced proliferation." (PMID 26097874, 2015). "In support of antionconcogenic role of S100A2, the expression level of this gene shown to be down-regulated in breast cancer, melanoma, prostate cancer, non-small cell lung cancer, esophageal squamous cell carcinoma and gastric carcinoma." (PMID 26097874, 2015). "On the other hand, S100A2 expression was found to be reduced as breast cancer progressed from carcinoma in situ to carcinoma." (PMID 22727333, 2012). "Though other S100 proteins have been shown to increase with retinoid therapy in models of cancer including teratocarcinoma, breast cancer, and gastric carcinoma, this is the first report of increased S100A2 expression by either rexinoids or TZDs." (PMID 19859558, 2010). "miRNAs are involved in the epigenetic regulation of S100A2 expression in breast cancer cells." (PMID 35885660, 2022). "Highly metastatic breast cancers exhibit elevated levels of S100A2 in vivo." (PMID 35885660, 2022). "S100A2 expression decreases in advanced breast cancer in vivo." (PMID 35885660, 2022). "Furthermore, our data confirmed that S100A6 and S100A2 were significantly increased in trastuzumab resistant breast cancer cells, SKBR3/100–8." (PMID 30736768, 2019). "S100A2 was identified as putative tumor suppressor gene in human breast cancer cell lines." (PMID 25419056, 2014). "Transcriptomic analysis revealed upregulation of macrophage activation markers, genes such as S100A8, S100A2, KRT81, KRT6C, MARCO and MMP1, as well as processes related to keratinization and the formation of a cornified envelope in breast cancer cells." (PMID 41073799, 2025). "Results showed that ionizing radiation and estrogen affected the expression of those genes that encoded the S100 calcium-binding proteins such as S100P, S100A14, S100A2, S100A8, and S100A9 in the immortalized breast cancer cell line MCF-10F." (PMID 39594999, 2024).
breast carcinoma (continued). "In saliva, three proteins of the S100A family, namely S100A2, S100A4, and S100A6, were among the most upregulated proteins in bitches with mammary tumors when compared to healthy controls." (PMID 32344524, 2020). "The analysis also indicated that S100A2 gene expression did not have significance in Basal breast cancer patients." (PMID 39594999, 2024). "Among these genes only the expression of S100A2 has been related to TAM treatment in breast cancer tissue but not in endometrium." (PMID 23874806, 2013). "S100A2 protein has previously been shown to be expressed in normal human breast epithelium, but not in human breast carcinoma cell lines." (PMID 11076656, 2000). "However, in our bioinformatics analysis, normal tissues had higher levels of S100A2 gene expression when compared to tumors, and other authors confirmed S100A2 protein expression in normal human breast epithelium, but not in breast carcinoma cell lines." (PMID 39594999, 2024).
colorectal cancer (17 papers, 2015 to 2025). A primary or metastatic malignant neoplasm that affects the colon or rectum. "Elevated S100A2 expression is associated with unfavorable clinical survival in colorectal cancer in vivo and tumor recurrence in vivo." (PMID 35885660, 2022). "Previous study has demonstrated that S100A2 had a deep relationship with the risk for colorectal cancer." (PMID 34122500, 2021). "Prior research has established that S100A2 plays a role in promoting metastasis in colorectal cancer and non-small cell lung cancer." (PMID 40092486, 2025). "Material and Methods: In this study, immunohistochemistry (IHC) was performed to identify the prognostic role of S100A2 protein expression in the tumour core of the tissue microarrays (TMAs) in colorectal cancer patients (n=787)." (PMID 37476187, 2023). "As an important paralog of S100A4, S100A2 is reported to be abnormally highly expressed in various tumors, such as colorectal cancer and lung cancer." (PMID 34530774, 2021). "Moreover, its overexpression has been detected in ovarian carcinomas and colorectal cancer, indicating that S100A2 critically affects cancer development." (PMID 37758734, 2023). "In colorectal cancer, S100A2 acts as a tumor promoter by modulating glycolytic reprogramming." (PMID 35042454, 2022). "Overexpression of S100A2 promotes glycolysis and proliferation of colorectal cancer cells." (PMID 34639069, 2021). "S100A2 protein overexpression has been identified as a prognostic indicator for patients diagnosed with stage II and III colorectal cancer." (PMID 38555418, 2024). "High S100A2 expression was previously reported to be an independent prognostic biomarker for poor prognosis in stage II and III colorectal cancer." (PMID 35042454, 2022). "The results showed that the expression of S100A2, DKK3 and SCHIP1, which play a role in colorectal cancer, HNSC, and gallbladder cancer, was significantly correlated with the expression of LINC00958." (PMID 36437914, 2022). "have reported that S100A2 activated the PI3K/AKT signaling pathway and upregulated GLUT1 expression in colorectal cancer, which induced glycolytic reprogramming and consequently increased tumor proliferation." (PMID 34887861, 2021). "A recent study showed that S100A2 is essential for colorectal cancer metastasis, consistent with earlier findings in non-small-cell lung cancer." (PMID 36114176, 2022). "S100A2 activates the phosphoinositide 3-kinase (PI3K)/AKT serine/threonine kinase (AKT) signaling pathway and upregulates GLUT1 expression, which induces glycolytic reprogramming and consequently increases the proliferation of colorectal cancer cells in vitro." (PMID 35885660, 2022).
gastric cancer (16 papers, 2004 to 2024). A primary or metastatic malignant neoplasm involving the stomach. "Similar results were reported in gastric cancer, loss S100A2 expression was significantly associated with poor prognosis and shown to be an independent predictor using multivariate analysis." (PMID 37476187, 2023). "S100A2 downregulation is significantly associated with poor differentiation, tumor invasion, and lymph node metastasis in vivo, and unfavorable survival in patients with gastric cancer in vivo." (PMID 35885660, 2022). "Similarly, gradual loss of S100A2 expression was found from gastritis, through intestinal metaplasia and dysplasia to gastric cancer." (PMID 26097874, 2015). "Consistently, the activation of this signaling pathway by S100A2 downregulation increases tumor invasion in gastric cancer cells in vitro." (PMID 35885660, 2022). "Gastric cancer is a common type of gastrointestinal cancer, and S100A2 expression is downregulated in gastric cancer in vivo." (PMID 35885660, 2022). "Of these, S100A2 has been implicated in CRC as a prognostic marker, and S100A10, itself a biomarker in CRC was shown to play a pivotal role in gastric cancer invasion." (PMID 34233735, 2021). "Studies have indicated that S100A2 can inhibit cell proliferation and invasion and act as a tumor suppressor involved in the occurrence and metastasis of gastric carcinoma, which is in agreement with our findings." (PMID 26106439, 2015). "Among them, S100A4 and S100A6 have been reported to be epigenetically up-regulated in nasopharyngeal and gastric cancer by DNA hypomethylation over their gene promoter regions, while S100A2 and S100A10 down-regulated in head/neck and pituitary cancer by DNA hypermethylation." (PMID 28498804, 2017). "S100A2 transfection in melanoma cells revealed its anti-proliferative activity, in gastric cancer cells it seems to decrease cell invasiveness, and similarly in head and neck squamous cell carcinoma S100A2 reduces proliferation, cell motility and cancer cell invasion." (PMID 26097874, 2015). "However studies are not consistent, as other reports show considerable levels of S100A2 mRNA and/or protein in non-small cell lung cancer, esophageal squamous cell carcinoma and Barrett's adenocarcinoma, and gastric cancer." (PMID 26097874, 2015). "It has been reported that S100A2 was highly expressed in non-small cell lung cancer, esophageal squamous cell carcinoma, laryngeal squamous cell carcinoma, ovarian serous papillary carcinomas, as well as gastric cancer." (PMID 18793447, 2008). "Until recently, S100A2 was thought to be the only protein in the S100 family that was negatively correlated with tumor initiation and progression; however, it was recently shown that high S100A2 expression is associated with FIGO stage as well as with histologic subgroups in gastric cancer." (PMID 35042454, 2022). "Through analysis of expression of S100A11 and S100A2 in gastric cancer, both of which contained EF-Hand structure, it was verified that p42.3 could participate in the occurrence and development of gastric cancer from both consistent and opposite to the p42.3 effect direction." (PMID 26106439, 2015). "Among them, four genes, including S100A2, S100A4, S100A7 and S100A10, were reported to overexpressed in gastric cancer previously." (PMID 18793447, 2008). "S100A2 acts as a tumor suppressor in gastric cancer, and it suppresses the extracellular-signal-regulated kinase (ERK) and mitogen-activated protein kinase (MAPK)/ERK kinase (MEK) signalling pathway, which is essential for the development of gastric cancer." (PMID 35885660, 2022). "Down-regulation of S100A2 protein in gastric carcinoma relative to the adjacent non-cancerous gastric tissues is reported by Ying Fu liu etal." (PMID 32099594, 2019). "In addition, molecular analysis has revealed that several S100s, including S100A2, S100A4, S100A7 and S100A10, exhibit altered expression levels in gastric cancer." (PMID 18793447, 2008).
gastric cancer (continued). "Both S100A2 and S100A10 genes were shown to be upregulated in gastric cancer of all three datasets." (PMID 18793447, 2008). "However, many lung adenocarcinomas and other nonsquamous cancers (for example, gastric carcinomas) strongly express S100A2." (PMID 15467767, 2004).
lung cancer (16 papers, 2004 to 2024). A malignant neoplasm involving the lung. "Activation of the EGF receptor, which is mutated in primary lung cancers selectively stimulates S100A2 gene expression, at the transcriptional level." (PMID 15467767, 2004). "Further functional analysis will be required to determine whether S100A2 might represent a novel therapeutic or diagnostic target in early lung cancer." (PMID 15467767, 2004). "Regarding the co-expression of S100A2 and PD-L1, studies have shown that overexpression of S100A2 in A549 lung cancer cells enhanced Akt phosphorylation." (PMID 34887861, 2021). "S100A2, for example, operates as a tumour suppressor in oral cancer while it promotes tumour growth in lung cancer." (PMID 32722137, 2020). "Diminished S100A2 expression has also been described in a cell line model study of early lung cancer and a number of other cancers, including head and neck cancer and skin melanoma." (PMID 15467767, 2004). "S100A2 functions as a tumor suppressor in oral cancer and as a tumor promoter in lung cancer." (PMID 33996571, 2021). "However, even within the lung cancer literature, there is disagreement regarding the prognostic significance of S100A2 expression." (PMID 19859558, 2010). "Notably, both lung cancer and normal bronchus tissue displayed strong signals of S100A2 staining." (PMID 38684596, 2024). "S100A2 seems to have a variable pattern of expression with some evidence pointing to higher expression in normal tissues and early or premalignant issues, but other types of cancer, such as lung cancer, have a higher expression in advanced lesions that correlate with poorer clinical prognosis." (PMID 19859558, 2010). "Overexpression of S100A2 also induced epithelial‐to‐mesenchymal transformation followed by enhanced invasion and increased AKT phosphorylation in A549 lung cancer cells." (PMID 28378523, 2017). "Protein S100-A2, is an EF hand calcium-binding protein, that is perturbed in several cancers and is also a TGF-β (transforming growth factor-β)-regulated gene in melanoma and lung cancer cells." (PMID 25419056, 2014). "In addition, S100A2 induced epithelial-mesenchymal transition (EMT), increased invasive capability, loosened colony morphology in soft agar, and enhanced Akt phosphorylation in A549 lung cancer cells to promote tumorigenic actions and tumor growth." (PMID 29607329, 2018). "In breast and lung cancers, treatment of cell lines with the demethylating agent 5-aza-2′-deoxycytidine led to the re-expression of S100A2 mRNA, indicating that the lack of S100A2 expression may be at least partially associated with aberrant methylation of the promoter region." (PMID 26097874, 2015).
melanoma (13 papers, 2009 to 2024). A malignant, usually aggressive tumor composed of atypical, neoplastic melanocytes. "S100A2 expression is higher in premalignant nevi than in cells from primary melanoma tumors or metastases suggesting that loss of S100A2 may be important for neoplastic transformation." (PMID 19859558, 2010). "S100A2 enhances the antitumor action of treatment with retinoid and thiazolidinedione against melanoma in vitro." (PMID 35885660, 2022). "S100A2 is highly expressed in primary melanoma, whereas its expression is low in metastatic melanoma cells in vivo." (PMID 35885660, 2022). "When using a xenograft mouse model, we showed that the overexpression of RAGE in WM115 human melanoma cells implanted in mice resulted in about 1.5 fold higher expression of S100A2 in tumor tissues, as compared to control tumors." (PMID 33256110, 2020). "We have demonstrated that S100A2 levels are low in the A375(DRO) melanoma cell line, and these levels are increased by treatment with PPARγ and RXR agonists, which is associated with a significant reduction in growth and increase in apoptosis." (PMID 19859558, 2010). "In summary, we have identified potential downstream mediators of rexinoid and TZD treatment in a poorly differentiated melanoma and found that alterations in S100A2 expression affect RXR and PPARγ signaling in A375(DRO) cells." (PMID 19859558, 2010). "Visual representation of the data indicated that cancerous tissues exhibited higher intensity of S100A2 staining in 10 tissue types including colon, testis, liver, pancreas, cervix, ovary, thyroid gland, endometrium, head and neck cancer, as well as melanoma and skin cancer." (PMID 38684596, 2024). "Earlier studies suggested that S100A2 plays the role of tumor suppressor in melanoma." (PMID 33256110, 2020). "Based upon the significant increase of S100A2 mRNA levels with each ligand alone and the synergistic increase with combination therapy, we performed additional experiments with S100A2 to define its role in mediating the effects of combination rexinoid/TZD treatment in melanoma cells." (PMID 19859558, 2010). "For example, S100B is a known marker of melanoma, and some other members of the S100A family, like S100A2 and S100A6, are thought to have a role in the progression of melanoma from normal melanocytes to metastatic disease." (PMID 38892279, 2024). "We had also observed lower levels of S100A2 transcripts in stage III and IV melanoma samples than in control skin samples." (PMID 33256110, 2020). "Modulators of retinoid receptors have been described in melanoma and include HSP 90 and Cyclophilin B, but we were unable to find any direct link between S100A2 expression and RXR regulation." (PMID 19859558, 2010). "We have identified the calcium binding protein S100A2 as a potential mediator of rexinoid and TZD signaling in melanoma." (PMID 19859558, 2010). "Indeed, in the context of melanoma xenograft tumors, we showed that overexpression of RAGE resulted in the upregulation of S100A2, S100A4, S100A6, and S100A10, both at the transcript and protein levels." (PMID 37627239, 2023). "Furthermore, S100A2 appears to be required for the maximal antiproliferative effects of rexinoids and TZD in these melanoma cells." (PMID 19859558, 2010). "However, with overexpression of S100A2, we observe an enhanced effect of rexinoid and TZD treatment on the melanoma cells." (PMID 19859558, 2010).
non-small cell lung carcinoma (12 papers, 2004 to 2025). A group of at least three distinct histological types of lung cancer, including non-small cell squamous cell carcinoma, adenocarcinoma, and large cell carcinoma. "S100A2 is a calcium-binding protein that belongs to the S100 family of acute-phase response factors and, when overexpressed in non-small-cell lung carcinoma cells subsequently injected subcutaneously in mice, has been shown to promote metastasis to the lungs." (PMID 24618895, 2014). "S100A2 differential expression has been observed in cancers such as laryngeal squamous cell carcinoma and non-small cell lung cancer." (PMID 21457566, 2011). "S100A2 was also shown to be a predictor of distant metastasis and survival rate in early-stage non-small cell lung cancer." (PMID 18793447, 2008). "S100A2 gene products were shown to be frequently and dramatically over-represented in non-small cell lung cancer (NSCLC) lesions over normal tissue by microarray analysis." (PMID 15467767, 2004). "Studies have confirmed that S100A2 participates in processes such as cell proliferation and migration in some tumors A previous study showed that high expression of S100A2 in patients with non-small cell lung cancer has a worse prognosis." (PMID 35432485, 2022).